LMNA (lamin A/C)
Diseases named in the same sentence as LMNA in open-access papers (continued):
Sharing a sentence is not in itself a finding about the gene and the disease.
Emery-Dreifuss muscular dystrophy (63 papers, 2004 to 2025). Emery-Dreifuss muscular dystrophy (EDMD) is characterized by muscular weakness and atrophy, with early joint contractures and cardiomyopathy. "Online Mendelian Inheritance in Man (OMIM) phenotype: Emery-Dreifuss muscular dystrophy 2 (OMIM#181350) is caused by heterozygous mutations in the LMNA gene (OMIM*150330)." (PMID 39737306, 2024). "This strategy was first proposed for Emery-Dreifuss muscular dystrophy, a disease that is caused by mutations in the lamin A/C gene (LMNA)." (PMID 35052837, 2022). "A homozygous mutant LmnaH222P/H222P mouse model based on a human mutation associated with Emery-Dreifuss muscular dystrophy has been the basis for much of the molecular mechanistic studies of LMNA-DCM." (PMID 34975533, 2021). "Many genetic mutations in the lamin A/C gene result in human diseases, such as Emery Dreifuss muscular dystrophy (EDMD), cardiomyopathy dilated (CDM1A), Dunnigan-type familial partial lipodystrophy (FPLD), and Hutchinson-Gilford progeria syndrome (HPGS)." (PMID 33396475, 2020). "The first disorder lamin A/C was ever found to be implicated in was Emery-Dreifuss muscular dystrophy (EDMD)." (PMID 33316938, 2020). "LMNA mutations have been associated with variable diseases including Emery-Dreifuss muscular dystrophy (EDMD), neuropathy, lipodystrophy, and progeria." (PMID 28182637, 2017). "LMNA mutations have been associated with several clinically distinct neuromuscular disorders including Emery-Dreifuss muscular dystrophy, limb girdle muscular dystrophy type 1B and Charcot-Marie-Tooth diseases type 2B1." (PMID 24892300, 2014). "The nuclear envelope proteins lamin A/C and emerin, mutations in which underlie Emery-Dreifuss muscular dystrophy, were also expressed in both quiescent and proliferating satellite cells." (PMID 19370151, 2009). "Emery-Dreifuss muscular dystrophy (EDMD) is inherited through mutations in either of two different genes: LMNA, encoding A-type lamins, and STA, which encodes a nuclear membrane protein named emerin." (PMID 15328537, 2004). "LMNA is ubiquitously expressed and mutations pleiotropic effects cause Charcot-Marie-Tooth disease, Hutchinson-Gildford progeria, limb-girdle muscular dystrophy, Emery-Dreifuss muscular dystrophy, and DCM with conduction system disease." (PMID 29367541, 2017). "Specifically, mutations in both lamin A (LMNA) and emerin (EMD) lead to Emery-Dreifuss muscular dystrophy (EDMD), utosomal dominant EDMD in LMNA mutations and X-linked EDMD in EMD mutations, both associated with cardiac arrythmia." (PMID 35784481, 2022). "LMNA mutations are responsible for autosomal forms of Emery-Dreifuss muscular dystrophy (EDMD), a disorder characterized by progressive muscle weakness and wasting associated with early contractures and dilated cardiomyopathy." (PMID 34433058, 2021). "Mutations in LMNA encoding A-type lamins, intermediate filament proteins of the nuclear envelope, cause autosomal Emery-Dreifuss muscular dystrophy (EDMD)." (PMID 34433058, 2021). "A-type lamins gene (LMNA) mutations cause an autosomal dominant inherited form of Emery-Dreifuss muscular dystrophy (EDMD)." (PMID 31341969, 2019). "It has been reported that LMNA mutations can cause autosomal forms of Emery-Dreifuss muscular dystrophy (AD-EDMD) and limb-girdle muscular dystrophy type 1B (LGMD1B), which show clinical features of proximal dominant muscle weakness." (PMID 30705772, 2019). "Emery-Dreifuss Muscular Dystrophy (EDMD) is genetically heterogeneous since it may be caused by a mutation in the STA gene encoding emerin (X-linked inheritance) or as AD trait determined by mutations in the LMNA gene encoding lamin A/C." (PMID 24065927, 2013). "The LMNA p.R388P and E358K mutations can cause L-CMD, whereas the two other LMNA mutations are responsible for the less severe phenotype of Emery-Dreifuss muscular dystrophy." (PMID 28125586, 2017).
Emery-Dreifuss muscular dystrophy (continued). "Emery-Dreifuss muscular dystrophy (EDMD) was initially linked to mutations in the EMD gene, which encodes the INM protein emerin, but can also be caused by mutations in LMNA and NE genes SYNE1, SYNE2 and TMEM43." (PMID 24490688, 2014). "Mutations in LMNA underlie a range of tissue-specific degenerative diseases, including those that affect skeletal muscle, such as autosomal-Emery-Dreifuss muscular dystrophy (A-EDMD) and limb girdle muscular dystrophy 1B." (PMID 21364987, 2011). "The patient denied a history of contractures in early childhood or progressive muscle weakness/wasting, thus a diagnosis of Emery-Dreifuss muscular dystrophy (caused by biallelic LMNA pathogenic variants) was not suspected." (PMID 40585884, 2025). "This was associated with the nuclear shape abnormalities, similar to lamin A/C knockout fibroblasts or EDMD (Emery-Dreifuss muscular dystrophy) patients." (PMID 26209045, 2016). "While specific SUN1 and SUN2 alleles have been directly connected to Emery-Dreifuss muscular dystrophy (EDMD) and related myopathies, SUN proteins may also have indirect effects in disorders in which the LMNA gene is mutated." (PMID 28747499, 2017).
Arrhythmia (38 papers, 2010 to 2026). Any cardiac rhythm other than the normal sinus rhythm. "Current recommendations advise that patients with left ventricular ejection fraction ≤ 40%, exercise-induced arrhythmias, or pathogenic variants in LMNA, TMEM43, or filamin C refrain from vigorous exercise or competitive sports, even if protected by an ICD." (PMID 41464586, 2025). "DCM caused by LMNA mutations is often accompanied by arrhythmias and conduction system abnormalities, which increase the risk of sudden death in patients." (PMID 39959410, 2025). "The study by Castrini AI and colleagues investigated the prevalence of cardiac dysfunction and arrhythmias in women with pathogenic or likely pathogenic variants of the genes encoding lamin A/C proteins (LMNA+)." (PMID 39408885, 2024). "In a study published in 2020, we showed that elevated serum levels of cardiac troponin T are often found in young LMNA mutation carriers as the first abnormality, preceding conduction defects and arrhythmias." (PMID 38892874, 2024). "For the carriers with LMNA mutations, cardiac dysrhythmias account for 92% of patients after the age of 30-year old." (PMID 35526016, 2022). "Cardiac involvement has been observed in patients carrying the LMNA mutated gene in the form of cardiac arrhythmias." (PMID 34066119, 2021). "Of note, differently from other idiopathic DCMs, those associated with LMNA mutations are characterized by a relatively greater occurrence of arrhythmias, including conduction system defects and a wide range of tachyarrhythmias." (PMID 29929425, 2018). "The clinical features, phenotypic spectrum, and types of LMNA mutations have been well-documented for isolated cardiac disease with arrhythmia and DCM." (PMID 27182706, 2016). "Two of 10 (20%) of the LMNA mutation-positive family members (subjects IV-6 and IV-8, respectively aged 14 and 12 years) were asymptomatic, free of significant arrhythmias, and revealed normal cardiac function." (PMID 25837155, 2015). "A meta-analysis of 299 patients with LMNA gene mutations found that 92% of patients had cardiac dysrhythmias after the age of 30 years, and there was sudden death in 42% of patients with the neuromuscular phenotype." (PMID 26098624, 2015). "The infrequent presence of double mutations has been reported in many human gene-causing diseases such as hypertrophic cardiomyopathy and arrhythmias associated with the lamin A/C (LMNA) gene." (PMID 24564502, 2014). "More than 40 mutations in the LMNA gene have been shown to be involved in the severity of the cardiac symptoms, characterized by conduction defect, arrhythmias, left ventricular (LV) dysfunction, dilation with heart failure or sudden death." (PMID 21151901, 2010). "Though clinical manifestations of cardiac arrhythmias and conduction abnormalities linked to LMNA variants have frequently been reported, there are only few reports of cardiac ion channels changes associated with LMNA genetic variants." (PMID 35935653, 2022). "In support of our hypothesis, we found that LMNA-mutated iPSC-CMs exhibit electrophysiological abnormalities including arrhythmias, and abnormal response to conditions causing elevated [Ca2+]i levels." (PMID 34360639, 2021). "92% of patients carrying LMNA gene mutations with either cardiac or neuromuscular phenotype were reported to present cardiac arrhythmias after the age of 30, 64% developed heart failure after the age of 50 and sudden death was the most common cause of death (46%)." (PMID 31208058, 2019). "Mutations in LMNA can lead to various cardiac diseases, including DCM, arrhythmias, and conduction system diseases." (PMID 39959410, 2025). "Other genes include lamin A/C (LMNA), linked to a high risk of arrhythmias and sudden cardiac death, filamin C (FLNC), phospholamban (PLN), β-myosin heavy chain (MYH7), cardiac troponin T (TNT2) and desmin (DES)." (PMID 41464586, 2025). "Patients with DCM carrying variants of LMNA, PLN, FLNC, and RBM20 have an increased risk of developing arrhythmias." (PMID 39959410, 2025).
Arrhythmia (continued). "Mutations in the LMNA and DSP genes, particularly associated with inflammation in ACM, require consideration of arrhythmia prevention strategies, such as ICD implantation." (PMID 41040932, 2025). "Eight of these associations were novel (LMNA, SMAD6, HSPB9, TMEM95, KLF1, TET2, NME3, KDM5B) and 5 genes have previously been linked to arrhythmias (SCN5A, TTN, RPL3L, PKP2, PMVK)." (PMID 38390584, 2024). "The 5-year-old son carried the LMNA Q517X mutant and was asymptomatic, free of arrhythmias, and showed normal cardiac function, thus suggesting incomplete and age-related penetrance of the mutation." (PMID 35846372, 2022). "Patient-derived hiPSC-CMs carrying LMNA mutations, especially frameshift mutation, are superior models replicating different DCM-related arrhythmia phenotypes and give the opportunities to elucidate the Lamin regulated-calcium handlings mechanism." (PMID 36082133, 2022). "The type of LMNA mutation may modify the risk of disease progression and arrhythmia; however, many human missense mutations appear to be extensively heterogeneous, but in particular, truncating mutations seem to have a higher risk for arrhythmia and sudden cardiac death." (PMID 32670084, 2020). "A mutation at the adjacent nucleotide in the same splice acceptor site, LMNA c.357-1G>T was reported in three patients with arrhythmia and DCM." (PMID 27182706, 2016). "In this study, we detected a novel LMNA gene mutation in a large family with arrhythmogenic cardiomyopathy of different phenotypes, including ARVC, DCM, conduction disturbances, arrhythmias, and sudden cardiac death (SCD)." (PMID 25837155, 2015). "In particular, myocardial fibrosis has been identified in the heart of LMNA mutation carriers experiencing arrhythmias or conduction disturbances, irrespective of LV dilation and/or dysfunction." (PMID 29929425, 2018). "In our case, the index patient (III.3) had two mutations: LMNA, p.V256V and SCN5A, p.R1583C.Therefore, we decided to insert an implantable cardioverter defibrillator (ICD), because of the incidence of two mutations and their high risk to get arrhythmia." (PMID 31453232, 2017). "Mutations in the LMNA gene are the most common cause of familial dilated cardiomyopathy (FDC) showing to be the severity of the cardiac symptoms, characterized by conduction defect, arrhythmias, LV dysfunction, and dilation with heart failure or sudden death." (PMID 21151901, 2010). "Six pediatric patients carrying a deleterious rare variant in LMNA concomitant with congenital heart disease (CHD) were previously found to have no major neuromuscular involvement Most cases showed a family history of CHD and/or DCM associated with arrhythmias." (PMID 36968203, 2023). "A study pinpointed that only one half of the patients carrying pathogenic or likely pathogenic LMNA mutations had a left ventricular fractional shortening <50%, suggesting that LMNA cardiomyopathy often manifests as a primary arrhythmia independent of muscle disease." (PMID 32245113, 2020). "After the age of 30, it is reported that up to 92% of patients bearing LMNA gene mutations present arrhythmias, including non-threatening manifestations like 1st degree AVB, frequent premature ventricular contractions (PVCs) or non-sustained ventricular tachycardia (NSVT)." (PMID 29929425, 2018).
familial partial lipodystrophy (33 papers, 2006 to 2025). "The adverse effect of a lack of lower limb/gluteofemoral fat on metabolism is strikingly apparent in patients with familial partial lipodystrophy, particularly types 2 and 3, due to specific mutations in LMNA and PPARG, respectively." (PMID 34875679, 2022). "A mutation in the LMNA gene has been shown to induce familial partial lipodystrophy of the Dunnigan type (FPLD)." (PMID 36205821, 2022). "Familial partial lipodystrophy, Dunnigan variety, is a recognised autosomal dominant disorder which is caused by heterozygous missense mutations in the lamin A/C gene." (PMID 25885670, 2015). "The first gene identified as causative of familial partial lipodystrophy (FPL) of the Dunnigan variety was lamin A/C (LMNA) gene, which remains the most common cause of FPL." (PMID 23766565, 2013). "Mutations in LMNA have been associated with a number of disorders, including familial partial lipodystrophy (OMIM 151660)." (PMID 21182758, 2010). "Mutations in the LMNA gene were associated with familial partial lipodystrophy." (PMID 27594807, 2016). "Familial partial lipodystrophy (FPLD) is a hereditary lipodystrophy commonly caused by mutations in the LMNA gene." (PMID 38739524, 2024). "While LMNA mutations are most commonly reported in patients with familial partial lipodystrophy (FPLD) of the Dunnigan variety, phenotypic heterogeneity exists in the distribution of body fat loss." (PMID 38887266, 2024). "Homozygous pathogenic mutations in the PPARG (3p25.2) or LMNA (1q22) genes cause a form of generalized lipodystrophy, while heterozygous carriers manifest a form of familial partial lipodystrophy (FPLD)." (PMID 37510094, 2023). "For example, lamin A/C (LMNA) is associated with Dunnigan-type familial partial lipodystrophy (FPLD; OMIM 151660) which is a rare monogenic form of IR." (PMID 29986445, 2018). "The first category includes tissues affected in an isolated manner such as striated muscle, peripheral muscle, and adipose tissue, e.g., lipodystrophy and familial partial lipodystrophy of the Dunnigan type (FPLD), which is caused due to a heterozygous mutation LMNA gene." (PMID 39202453, 2024). "Finally, we investigated if rare variants in known familial partial lipodystrophy genes PPARG and LMNA were associated with the adiposity traits defined in this study 8,10,69." (PMID 35773277, 2022). "Muscular metabolic defects in fatty acid and glucose metabolism have been shown for FPLD (familial partial lipodystrophy) and LGMD1B (Limb-girdle muscular dystrophy) patients, and some evidence of mitochondrial dysfunction were shown in human fibroblasts expressing LMNA mutations." (PMID 32906763, 2020). "In addition, serum levels of total cholesterol, HDL, and LDL cholesterol as well as triglyceride levels were altered in LMNA-KO rabbits, which have been reported in patients with familial partial lipodystrophy." (PMID 30705772, 2019). "Regarding Familial Partial Lipodystrophy (FPLD), the main subgroups, FPLD2 to 6, are associated with pathogenic variants in LMNA, PPARG, PLIN1, CIDEC and LIPE respectively, whereas FPLD1 is thought to be of polygenic origin." (PMID 38678257, 2024). "Further studies have shown that LMNA interacts with the adipocyte differentiation factor, sterol regulatory element-binding protein 1 (SREBP-1), and that the reduced binding of LMNA to SREBP1 may be the cause of the familial partial lipodystrophy." (PMID 27594807, 2016). "Partial lipodystrophy syndromes are classified into Familial Partial Lipodystrophy (FPLD) including FPLD1 (Köbberling syndrome), FPLD2 (Dunnigan syndrome, due to mutations in the LMNA gene), FPLD3 (PPARG gene), FPLD4 (PLIN1 gene), FPLD5 (CIDEC gene), FPLD6 (LIPE gene) gene mutations." (PMID 41341138, 2025).